USP17L27 (ubiquitin specific peptidase 17 like family member 27)
Description:
Deubiquitinating enzyme that removes conjugated ubiquitin from specific proteins to regulate different cellular processes that may include cell proliferation, progression through the cell cycle, apoptosis, cell migration, and the cellular response to viral infection.
Target class: Enzyme; Hydrolase
Gene: Protein-coding gene on chromosome 4 (9,344,148 to 9,345,740, forward strand). Ensembl gene ENSG00000235780.
Subcellular location: Nucleus, nucleolus; Endoplasmic reticulum
Pathways (Reactome):
Metabolism of proteins: Ub-specific processing proteases
Gene Ontology:
Molecular function: cysteine-type deubiquitinase activity; hyaluronic acid binding; RNA binding
Biological process: positive regulation of epithelial cell apoptotic process; protein deubiquitination involved in ubiquitin-dependent protein catabolic process; regulation of apoptotic process; protein deubiquitination
Cellular component: nucleolus; nucleus; endoplasmic reticulum
Homologues: Paralogues in human: USP17L24 (100% identical), USP17L25 (100% identical), USP17L26 (100% identical), USP17L28 (100% identical), USP17L29 (100% identical), USP17L30 (100% identical), USP17L5 (99% identical), USP17L20 (99% identical), USP17L11 (99% identical), USP17L17 (99% identical), USP17L18 (99% identical), USP17L22 (99% identical), and 59 more.
Diseases named in the same sentence as USP17L27 in open-access papers:
USP17L27 is named in the same sentence as 1 disease in open-access papers, as found by Europe PMC text mining. Sharing a sentence is not in itself a finding about the gene and the disease.
USP17L27 shares sentences with these, for which no sentence is quoted: viral infection (1 paper).